MATR3 (matrin 3)
Diseases named in the same sentence as MATR3 in open-access papers (continued):
Sharing a sentence is not in itself a finding about the gene and the disease.
developmental delay (1 paper, 2022). "While the AHDC1 mutation is likely the source of developmental delay, creation of a genetrap construct in exon 13 of the mouse Matr3 gene revealed a key role for Matr3 in cardiovascular development." (PMID 34350653, 2022). "Genetic examination of a novel proband exhibiting developmental delay and cardiovascular defects including PDA revealed mutations in both AHDC1 and Matrin 3 (MATR3)." (PMID 34350653, 2022).
erythroleukemia (1 paper, 2021). Acute erythroid leukemia characterised by the presence of at least 50% erythroid precursors and at least 20% myeloblasts in the bone marrow. "As a first step in assessing how the inner nuclear protein Matrin-3 (Matr3) impacts nuclear structure and gene expression, we deleted the entire gene body by CRISPR/Cas9 in mouse erythroleukemia (MEL) cells." (PMID 34716321, 2021).
facioscapulohumeral muscular dystrophy (1 paper, 2024). An autosomal dominant disorder affecting the skeletal muscles of the face, scapula, and upper arm. "Beyond cancer, MATR3 has also been reported to have ties to other diseases, such as facioscapulohumeral muscular dystrophy (FSHD)." (PMID 38891112, 2024).
familial disease (1 paper, 2018). "Additionally, post-mortem analyses demonstrated MATR3 pathology—consisting of cytoplasmic MATR3 accumulation as well as strong nuclear immunostaining—in patients with sporadic ALS and familial disease due to C9orf72 hexanucleotide expansions and FUS mutations." (PMID 30015619, 2018).
fragile X syndrome (1 paper, 2016). A genetic syndrome caused by mutations in the FMR1 gene which is responsible for the expression of the fragile X mental retardation 1 protein. "The interactors hnRNPA1, hnRNPA2B1, Matr3, FMRP and Prkra have previously been associated with neurodegenerative diseases (ALS, multisystem proteinopathy, fragile X-associated tremor/ataxia syndrome (FXTAS), fragile-X syndrome (FXS) and dystonia parkisonism)." (PMID 27164932, 2016).
fungal keratitis (1 paper, 2023). "We identified 60 viral genes and 327 bacterial/fungal genes with an AUC of at least 0.9, among them MATR3, CXCL9, and KCNA3 for viral keratitis, and S100A8, CXCL8, and CCL20 for bacterial/fungal keratitis." (PMID 38274739, 2023). "MATR3 (AUC = 0.95), CXCL9 (AUC = 0.95), and KCNA3 (AUC = 0.90) were among the best candidate markers for viral keratitis, and S100A8 (AUC = 1), CXCL8 (AUC = 1), and CCL20 (AUC = 1) were among the best candidates for bacterial/fungal keratitis." (PMID 38274739, 2023).
glioma (1 paper, 2022). A benign or malignant brain and spinal cord tumor that arises from glial cells (astrocytes, oligodendrocytes, ependymal cells). "However, the research progressed on circRNA from MATR3 in glioma remains unreported." (PMID 36570001, 2022).
heart defects (1 paper, 2023). "Interestingly, MATR3 was found highly expressed in cardiomyocytes from newborn mice and heterozygous mutations in MATR3 resulted in congenital heart defects." (PMID 36877136, 2023).
Hemophagocytosis (1 paper, 2022). Phagocytosis by macrophages of erythrocytes, leukocytes, platelets, and their precursors in bone marrow and other tissues. "We analyzed NFκB and MATR3 mRNA expressions in the PB mononuclear cells of patients with hemophagocytosis and healthy volunteers." (PMID 36140262, 2022).
lymph node metastasis (1 paper, 2023). "We showed that low MATR3 mRNA levels were associated with poor prognosis features such as advanced T-stage and lymph node metastasis." (PMID 36830863, 2023).
lymphoma (1 paper, 2021). A malignant (clonal) proliferation of B- lymphocytes or T- lymphocytes which involves the lymph nodes, bone marrow and/or extranodal sites. "In chicken lymphoma cells, for example, both arms of a bipartite NLS are necessary for targeting MATR3 to the nucleus, while in rat Ac2F cells, a separate stretch of positively charged aa in the middle of the C-terminal IDR drives MATR3 nuclear localization." (PMID 33427209, 2021).
male infertility (1 paper, 2020). The inability of the male to effect fertilization of an ovum after a specified period of unprotected intercourse. "CFTR, mutations of which are associated with male infertility, might be coregulated by FXR1, HNRNPA1, MATR3, PABPC1, G3BP2, FMR1, and SRSF7." (PMID 32316190, 2020).
Marfan syndrome (1 paper, 2020). A disorder of the connective tissue. "A few of them are known to cause syndromic forms of cervical insufficiency associated with collagen disorders such as EDS, Marfan syndrome, restrictive dermopathy, and myopathy due to MATR3 mutations." (PMID 32214361, 2020). "Altogether, only 17 genes were primarily identified in relation to cervical insufficiency, with six being syndromic, i.e. COL1A1 and COL3A1 causing EDS; FBN1 causing Marfan syndrome; ZMPSTE24 and LMNA causing restrictive dermopathy; and MATR3 causing myopathy." (PMID 32214361, 2020).
Mitochondrial myopathy (1 paper, 2021). "CHCHD10 G58R and CHCHD10 G66V were identified in mitochondrial myopathy and late-onset spinal muscular atrophy such as VCP and Matrin 3 (MATR3), which also exhibit clinical pleiotropy, including myopathy." (PMID 33805659, 2021).
Myalgia (1 paper, 2020). "Noteworthy, MATR3-patients at disease onset (presymptomatic or myalgia only) did not match with the MATR3-pattern." (PMID 32361838, 2020).
Paget’s disease of bone (1 paper, 2015). "FTD in combination with inclusion body myopathy and Paget’s disease of bone in the patients or families strongly suggests mutations in the VCP, hnRNPA1, or MATR3 genes." (PMID 26213621, 2015).
rectal cancer (1 paper, 2023). A primary or metastatic malignant neoplasm that affects the rectum. "In summary, we identified five radiosensitivity-related genes associated with rectal cancer prognosis: TOP2A, MATR3, APOL6, JOSD1, HOXC6." (PMID 38012642, 2023). "In subsequent studies, we will perform cell function experiments, xenograft experiments in nude mice, and molecular mechanism experiments on irradiated human rectal cancer cell lines after overexpression or knockdown of TOP2A, MATR3, APOL6, JOSD1, and HOXC6." (PMID 38012642, 2023). "Through the random survival forest analysis of these 1153 differential genes, we finally screened five key genes, which were the radiosensitivity up-regulated genes of rectal cancer: TOP2A, MATR3, APOL6, JOSD1 and the radiosensitivity down regulated gene of rectal cancer: HOXC6." (PMID 38012642, 2023). "We found that TOP2A, APOL6, MATR3 were correlated with MSI and could be used as potential indicators of sensitivity to immunotherapy for rectal cancer." (PMID 38012642, 2023). "qRT-PCR revealed that MATR3 expression was different in rectal cancer tissues and adjacent non-cancerous tissues, while APOL6, HOXC6, JOSD1, and TOP2A expression was not different." (PMID 38012642, 2023).
Stroke (1 paper, 2023). Sudden impairment of blood flow to a part of the brain due to occlusion or rupture of an artery to the brain. "Co-expressed hub genes of EIF4E3, ZNF595, ZNF700, MATR3, ACKR4, ANXA3, SEPSECS-AS1, and RNF166 were significantly associated with AF-related stroke." (PMID 36952494, 2023). "Based on the results of DEG3 and ROC curves in GSE66724 and GSE58294, we filtered eight hub genes of AF-related stroke (AUC > 0.8), including EIF4E3, ZNF595, ZNF700, MATR3, ACKR4, ANXA3, SEPSECS-AS1, and RNF166." (PMID 36952494, 2023). "The hub genes of EIF4E3, ZNF595, ZNF700, MATR3, ACKR4, ANXA3, SEPSECS-AS1, and RNF166 may link AF and secondary stroke." (PMID 36952494, 2023). "Hub genes EIF4E3, ZNF595, ZNF700, MATR3, ACKR4, ANXA3, SEPSECS-AS1, and RNF166 have potential as novel biomarkers and therapeutic targets in AF-related stroke." (PMID 36952494, 2023).
myopathy (22 papers, 2015 to 2024). A disease of the muscle in which the muscle fibers do not function properly. "In all our patients, the disease is caused by a recurrent pathogenic missense variant p.S85C in the MATR3 gene, as observed in all previously reported cases of this myopathy." (PMID 39192891, 2024). "MATR3 mutation-associated myopathy was associated with the same distal limb weakness as previous SQSTM1-related cases, while the present case revealed proximal myopathy." (PMID 36998782, 2023). "Another outstanding question concerns the phenotypic spectrum of MATR3-linked disease and how MATR3 mutations can cause motor neuron degeneration, cortical neuron loss, and/or myopathy." (PMID 33427209, 2021). "A comprehensive pattern of muscular involvement in MATR3-associated myopathy was defined on the basis of the Fischer grading system (for details see “Methods” section)." (PMID 32361838, 2020). "Overall, our results indicate that increasing the levels of MATR3 in muscle can cause pathologic changes associated with myopathy, with MATR3F115C expression causing overt muscle atrophy and a profound motor phenotype." (PMID 30563574, 2018). "The ability of ALS-linked F115C MATR3 to cause overlapping pathologies and phenotypes to human VCPDM indicates that humans bearing any MATR3 mutation should be examined for myopathy." (PMID 30563574, 2018). "Patients harboring the S85C mutation in MATR3 initially present with myopathy in the muscles of the hands and feet and have a slowly progressing disease that leads to respiratory failure and death after 15 years of illness." (PMID 30563574, 2018). "For these studies, we used mouse C2C12 myoblast cells, which represent a relevant cell type for myopathy associated with MATR3 mutations." (PMID 29511296, 2018). "Based on the grading system applied, a comprehensive pattern of muscular affection in MATR3-associated myopathy could be established, that showed a feasible match to the individual patients." (PMID 32361838, 2020). "While MATR3 immunoreactivity appears to be higher in a few ALS and myopathy patient tissues, further analysis of patient tissues, and/or discovery of a duplication mutation in MATR3 resulting in similar phenotypes, is required to validate the gain-of-function models." (PMID 32811564, 2020). "In the present study, we used both immunostaining of transfected cells and expression of Matrin 3 fused to yellow fluorescent protein (YFP), to determine whether mutations in Matrin 3 that cause ALS/myopathy changes the subcellular localization of the protein." (PMID 26528920, 2015). "More recently, Matrin 3 has been shown to co-immunoprecipitate with lamin-A, a nuclear matrix intermediate filament; lamin-A mutations have been identified as a common cause of myopathy." (PMID 26528920, 2015). "Similarly, mice that harbor the S85C mutation in the mouse Matr3 gene also show robust phenotypes, including motor function defects, muscle atrophy, and early death, suggesting that the S85C mutation is a genetic determinant of myopathy and ALS." (PMID 38891112, 2024). "Thus, a sufficient delineation to MATR3-associated myopathy appears feasible." (PMID 32361838, 2020). "The observed selective involvement of the thoracic segments of paraspinal musculature corresponds very well to the camptocormia frequently observed in advanced disease stages of MATR3 myopathy (unpublished observation)." (PMID 32361838, 2020). "Although the underlying mechanisms remain elusive, the results emphasize the role of ISR and stress granule formation in the pathogenesis of MATR3 myopathy." (PMID 32823799, 2020). "Nonetheless, additional prospective studies including newly identified individuals with MATR3-myopathy are needed to further address this issue." (PMID 32361838, 2020).
myopathy (continued). "Cytoplasmic aggregates of the stress granule proteins TIA1 and Ras GTPase-activating protein-binding protein 1 (G3BP1) are observed in muscle biopsy specimen of MATR3-myopathy, suggestive of defects in stress granule formation or dynamics." (PMID 32823799, 2020). "Among the pathogenic mutations studied here, only the S85C mutation significantly affected MATR3(∆RRM2)-EGFP droplet viscosity; notably, S85C is also the only disease-associated mutation associated with a primary myopathy as well as neurodegeneration." (PMID 30015619, 2018). "Multiple mutations in Matrin 3 have been associated with ALS and paralytic disease caused by myopathy." (PMID 26528920, 2015). "One limitation of these Tg mice is that there are no reported cases of myopathy or ALS in humans caused by an overexpression of MATR3." (PMID 30563574, 2018). "However, a selective involution of gluteus minimus muscle as in MATR3-associated myopathy was not described." (PMID 32361838, 2020). "Thus, they might be easily distinguished from MATR3-myopathy that usually shows an onset between 30 and 40 years of age." (PMID 32361838, 2020). "Notably, MATR3 S85C has also been associated to VCPDM in several additional families with or without similar neurogenic features, suggesting that this mutation may cause a spectrum of phenotypes ranging from pure myopathy to motor neuron disease." (PMID 38891112, 2024). "Distal myopathy occurred in 10 patients (5 TIA1, 2 SQSTM1 + TIA1, 1 MATR3, 1 HNRNPA1, 1VCP)." (PMID 36861178, 2023). "Our findings indicate that mutations in Matrin 3 that are associated with ALS and myopathy do not dramatically alter the normal localization of the protein or readily induce inclusion formation." (PMID 26528920, 2015). "Interestingly, none of the myopathies with potential distal phenotype showed a relevant congruency to MATR3-myopathy." (PMID 32361838, 2020).
neurodegenerative disease (11 papers, 2016 to 2025). A disorder of the central nervous system characterized by gradual and progressive loss of neural tissue and neurologic function. "Loss of Matr3 has been associated with increased cryptic exon inclusion, contributing to neurodegenerative diseases." (PMID 40790242, 2025). "Potentially because of the similarity between MATR3 and other neurodegenerative disease–associated RBPs, the majority of investigations to date have focused on MATR3’s influence on pre-mRNA splicing and RNA regulation." (PMID 33427209, 2021). "Mutations in various RNA binding proteins such as hnRNP A1, hnRNP A2/B1, FET protein family (FUS, TAF-15, EWSR1) Matrin-3, TIA-1 and Ataxin-244 are implicated in various neurodegenerative diseases." (PMID 29070802, 2017). "Retrotransposons are not often implicated in neurodegenerative diseases; thus, it is crucial to clarify the potential role of this MATR3 variant 5 retrotransposition in early-onset FTD." (PMID 33408686, 2020).
tumor (11 papers, 2017 to 2026). "To further elucidate the underlying mechanism by which MATR3 functions as a putative tumor suppressor, we explored the signaling pathway altered by MATR3." (PMID 32977861, 2020). "To elucidate the underlying mechanism by which MATR3 functions as a tumor suppressor, we performed Tandem affinity purification followed by mass spectrometry (TAP-MS) and pathway analysis." (PMID 32977861, 2020). "RNF157-mediated ubiquitination promotes DHX58 degradation, thereby accelerating tumor proliferation, whereas MATR3 enhances carcinogenesis by inhibiting DHX58-dependent IFN-I signaling." (PMID 41569991, 2026). "On the other hand, there are also a few studies reporting an opposite role for MATR3, suggesting its tumor-suppressor-like function." (PMID 38891112, 2024). "The association of low MATR3 expression with worse survival is consistent with a tumor suppressive profile; nevertheless, our investigation does not allow us to conclude anything definitive about the character of MATR3 functionality in ccRCC." (PMID 36830863, 2023). "Twenty samples (18.69%) of tumor tissue were characterized by low MATR3 expression and 87 (81.31%) by high." (PMID 36830863, 2023). "The present study aimed to elucidate the potential tumor-suppressive function of MATR3, an abundant nuclear protein, in BLBC/TNBC, whose cancer-relevance has not been characterized." (PMID 32977861, 2020). "We observed DHX9 and MATR3 (in Tumor A, set 1), HNRNPC and LARP1 (in Tumor A, set 2), SRSF1 (in Tumor B, set 1 & Tumor B, set 2), SRSF6 and IGF2BP2 (Tumor B, set 2), HNRNPU (in Tumor B, set 2 & Tumor C, set 2), and FAM120A and HNRNPA2B1 (in Tumor C, set 2)." (PMID 31892958, 2020). "MATR3 protein and mRNA levels were lower in tumor tissues compared to control tissues." (PMID 36830863, 2023). "Undoubtedly, our findings highlight the role of MATR3 in tumor progression." (PMID 36830863, 2023). "Collectively, our results demonstrate that MIDEAS-AS1 serves as a tumor-suppressor in TNBC through modulating MATR3/NCALD axis, and MIDEAS-AS1 may function as a prognostic biomarker for TNBC." (PMID 37770991, 2023). "Our data demonstrate that MATR3 functions as a putative tumor suppressor in BLBC/TNBC cells." (PMID 32977861, 2020). "The data suggest that MATR3 functions as a putative tumor suppressor and next we scrutinized whether MATR3 expression has clinical relevance." (PMID 32977861, 2020). "For example, TFs, such as ASH1L, CFLAR, HMGB3, ZNF160 and MATR3, displayed opposite behaviors on some cytokines; inflammatory factors; nuclear and tumor factors, such as IL-2, IL-6, NF-κB, and Irf3; immunogenic nucleic acids; papillomavirus E7/E6; caspase-3/caspase-8; Toll-like receptor; and so on." (PMID 28719625, 2017). "Also, we found that oncogenic YAP/TAZ pathway is the most significantly altered by MATR3 from pathway analysis, and validated that YAP/TAZ target genes were suppressed by MATR3, which suggests that MATR3 functions as a tumor suppressor potentially by regulating YAP/TAZ pathway." (PMID 32977861, 2020). "In this sense, MATR3 with potential tumor-suppressive function could serve as a biomarker to predict the efficacy of chemotherapy that promotes BLBC cellular apoptosis; BLBC with high MATR3 levels may enhance the efficacy of chemotherapeutic agents by promoting apoptosis." (PMID 32977861, 2020). "Among them, CTNNA1, encoding α-catenin, has been shown to have tumor-suppressive functions in E-cadherin-negative BLBC, which suggests that MATR3 may also function as a tumor suppressor gene but its role in cancer remains elusive." (PMID 32977861, 2020).